RB1 (RB transcriptional corepressor 1)
Diseases named in the same sentence as RB1 in open-access papers (continued):
Sharing a sentence is not in itself a finding about the gene and the disease.
cancer (continued). "We further show that for many of the RB1 SL genes validated in human cancer cell lines, low activity of the SL gene in human tumors, when concurrent with low levels of RB1 was associated with improved patient survival." (PMID 33591981, 2021). "In support of this notion, exploration of data from genomics of drug sensitivity in cancer database showed that loss-of-function mutation of RB1 had highest rank in driving CDK4/6i (palbociclib) resistance across hundreds of cancer cell lines." (PMID 34508104, 2021). "Further, a pharmacogenomic screen identified LY3295668, a highly specific Aurora A inhibitor that specifically kills RB1-deficient cancer cells." (PMID 33591981, 2021). "Five patients had non-RB1 cancer-associated germline mutations in keeping with other cancer cohorts in which 12–17.5% patient had germline mutations." (PMID 33466343, 2021). "Next, we further filtered this list to only retain orthologs of these genes that more efficiently suppress proliferation of human RB1-deficient cancer cell lines, as identified based on publicly available large-scale shRNA and CRISPR screen data." (PMID 33591981, 2021). "Inhibition of TSC2 in RB1-deficient cancer cells increased oxidative stress in a superoxide dismutase 2 (SOD2)-dependent manner, causing apoptosis." (PMID 34359636, 2021). "Leiomyosarcoma, osteosarcoma, and melanoma are the most common second primary cancers in patients with germline RB1 mutations." (PMID 32218800, 2020). "Ostensibly these data reflect positive-selection associated with RB1 loss and is consistent with the finding that RB1 loss occurs more frequently in metastatic advanced cancers of this type (e.g., prostate and breast) and is associated with poor outcome." (PMID 32242058, 2020). "RB1 encodes the RB transcriptional co-repressor 1, which is mainly related to the cell cycle and different types of cancer, besides heterochromatin formation, cellular senescence and DNA damage response." (PMID 32055858, 2020). "Due to its crucial role in cell cycle control, mutational inactivation of RB1 is a cancer driver in many types of cancer." (PMID 33037191, 2020). "AURKA inhibition turns the stathmin to a lethal weapon (active, dephosphorylated form) in RB1-deficient cancer cells, killing the cells by disrupting microtubule dynamics." (PMID 33037191, 2020). "Single copy loss on chromosome 13q encompassing the RB1 locus is prevalent in many cancers, yielding reduced expression of multiple genes in cis, and is inversely related to the CDK4/6-RB integrated signature supporting a cause-effect relationship." (PMID 32242058, 2020). "The RB1 gene is a fundamental cell cycle regulator, whose inactivation is notoriously associated with cancer development." (PMID 33194654, 2020). "In summary, this study proposes the agents targeting microtubule dynamics, including AURKA inhibitors, as potential anticancer drugs for the treatment of RB1-deficient cancer, such as SCLC." (PMID 33037191, 2020). "Consistent with the mutual exclusive relationship between RB1 and CDKN2A gene alterations, the genes are inversely expressed in most cancers exhibiting frequent loss/mutation of RB1." (PMID 32242058, 2020). "Studies have reported that mitochondrial respiration is upregulated in cancer cells with RB1 deficiency, HRAS mutations, and BCL-2 overexpression." (PMID 33235318, 2020). "Using the cbioportal, we found that among 31 subtypes of cancer, 30% exhibit defects in the RB pathway, with 7% of the patients exhibiting a loss of RB1." (PMID 33114224, 2020).
cancer (continued). "The functional relationship between gene expression signatures linked to RB activity and actual RB1 loss in cancer has been limited with disparate conclusions." (PMID 32242058, 2020). "Inhibition of AURKA activity activates stathmin and strongly facilitates microtubule depolymerization in RB1-deficient cancer cells, severely impacting the spindle formation and triggering mitotic cell death." (PMID 33037191, 2020). "MYC and RB1 overwhelmingly feature either heavy gene amplifications or heavy deletions and mutations, respectively, across different cancer types." (PMID 33266490, 2020). "Recent evidence showed that oxidative phosphorylation is upregulated in some cancers, including breast cancer, Hodgkin lymphoma and RB1-deficient cancers." (PMID 32111066, 2020). "Usually diagnosed in children under the age of three, RB comprises an important subject in cancer genetics research due to its distinct association with the RB1 tumor suppressor gene." (PMID 31835688, 2019). "The RB1 gene, which codes for pRB, is inactivated or mutated in many forms of human cancer, resulting in enhanced, or deregulated E2F activity, due to loss of pRB function." (PMID 29855511, 2018). "The retinoblastoma susceptibility gene (RB1), the tumor suppressor gene, is mutated at variable frequencies in numerous human cancers." (PMID 30680063, 2018). "Another limitation in using the combinatory treatment (CDK4/6 inhibitors and DNA damaging agents) is the deficiency of RB1 in some primary cancer cells, which has been linked to poor prognosis and altered response to anticancer treatment." (PMID 29306194, 2018). "The second cluster was enriched with the RB1 deletion (100%; P = 0.002, Fisher’s exact test), which accelerates additional cancer gene mutations in sarcomagenesis." (PMID 30598078, 2018). "This concept is underscored by the fact that no targeted knock in strain recapitulates the complete proliferative control and cancer susceptibility phenotypes of Rb1−/− mice." (PMID 28293272, 2017). "This includes a loss at 1q42.2-q42.3 which contains ARID4B, a chromatin-remodeling gene that interacts with RB1, and reduced expression is associated with the development of breast and other cancers." (PMID 28945760, 2017). "Together, these studies identify p16 loss as a molecular event that causes genetic instability in addition to inactivating RB1 function thus providing an explanation for why p16 is preferentially targeted in human cancers." (PMID 28414317, 2017). "We believe that our case adds to growing evidence across multiple cancer types that RB1 loss is predictive of chemosensitivity, perhaps in particular to platinum-based regimens." (PMID 28390395, 2017). "Exome sequencing revealed an inactivating mutation in RB1 which we believe to be the first such mutation to be reported in this cancer type." (PMID 28390395, 2017). "Such an inheritance of the mutant RB1 allele results in a 97% risk of developing the disease and a high lifelong risk of secondary cancers." (PMID 28575107, 2017).
cancer (continued). "To date, the RB1 pathway in human cancers has been reported to be disrupted only by loss of expression of CDKN2A or RB1, as well as by CDK4/CCND1 over- expression, even though SWI/SNF is known to be an essential cofactor for RB1 function." (PMID 28105458, 2016). "The idea that RB1 mutation has such far-reaching effects is consistent with the fact that this change is sufficient, in some contexts, to cause cancer." (PMID 27401552, 2016). "The Rb1 pathway is altered in almost 70% of human cancer types and this pathway is mutated in 78% of cases of GBM." (PMID 27344175, 2016). "Another study has reported that an inactive RB1 pathway, a hallmark of cancer, is associated with accumulation of Akt oncogene." (PMID 27226982, 2016). "Among these, RB1 has been implicated in the regulation of apoptosis, the alteration of which underlies both cancer development and resistance to therapy." (PMID 26160835, 2015). "In particular, RB1 deficiency seems to be associated with improved cytotoxic response to DNA damaging agents, at least for some cancer types." (PMID 26160835, 2015). "In the second approach, to select for proliferation stimulated genes, we used the criterion ‘fold change > 2’ in combination with significant P-values based on their behaviour in RB1-linked cancers." (PMID 25161863, 2014). "RB1 is mutated or lost in other common cancers, including small cell lung cancer and breast, and inactivated through binding and destabilization by the human papillomavirus (HPV) transforming protein E7 in the majority of cervical cancers." (PMID 23516486, 2013). "Rb1+/− mice are highly predisposed to cancers of neuroendocrine origin including pituitary (intermediate and anterior lobe), thyroid C-cell (which can metastasize to lung), and adrenal." (PMID 23454836, 2013). "RB1 function is thought to be compromised by mutation of the upstream regulatory network in the majority of sporadic cancers." (PMID 23516486, 2013). "RB represents one of the rare cancers in which the initiating genetic lesion (RB1 loss of function) is known." (PMID 23233862, 2012). "Persons heterozygous for a germline RB1 mutation are predisposed to cancer of the developing retina with a rate and penetrance unmatched in any other tissue." (PMID 22336108, 2012). "Dysfunction of the retinoblastoma (RB1) gene, which maps to chromosome 13q14, has been associated with increased risk for cancer-specific death, in patients who have survived at least five years from diagnosis." (PMID 23056464, 2012). "Direct measurement of RB1 by IHC has generated vast amounts of information on RB1 deficiency in many types of cancers; however, it has several drawbacks as a biomarker to predict RB1 status." (PMID 21447152, 2011). "The functional loss of RB1 is recognized to be one of the hallmarks that differentiate cancer cells from normal cells." (PMID 21447152, 2011). "In this study we sought to identify cancer-associated mutations that specifically target the region of RB1 encoding the LXCXE binding cleft." (PMID 20298605, 2010). "Somatic point mutations in RB1 have been detected in different malignancies including bladder and prostate cancer." (PMID 20594292, 2010). "Loss of RB1 occurred with a similar frequency in early-stage and low-grade cancers as in more advanced cancers." (PMID 7526887, 1994). "Cancers with RB1 or STK11 deficiencies show sensitivity to PARP inhibition." (PMID 41541668, 2026).
cancer (continued). "The conclusion that RB1 loss increases dependence on BCL-XL is also strongly supported by large scale drug screening data from the Sanger Institute Genomics of Drug Sensitivity in Cancer and Broad DepMap." (PMID 40436896, 2025). "Similarly, mutational and structural defects in RB1 are frequently observed in many cancers accounting for up to 25% of bladder cancer (BLCA) and sarcomas." (PMID 40138429, 2025). "Somatic retinoblastoma 1 (RB1) loss is prevalent across different cancer types and is enriched in treatment‐refractory tumors, such as castration‐resistant prostate cancer (CRPC) and small‐cell lung cancer, but cannot be considered as a direct druggable target." (PMID 40904703, 2025). "Given the important role of RB1 deficiency in cancer development and progression, numerous genomic studies, such as The Cancer Genome Atlas (TCGA), have revealed the prevalence of somatic alterations (e.g., mutations and CN loss) in the RB1 gene." (PMID 40904703, 2025). "We also show that RBness cancers have a transcriptional program that is correlated with genes that are known to be synthetic lethal with RB1 mutation, suggesting new ways these cancers that phenocopy RB1 defects could be treated." (PMID 40138429, 2025). "Additionally, our analysis revealed longer PFS in patients with high NK cells, interferons, and RB1 mutations, whereas high cancer-associated fibroblasts levels and mutations in the mTOR signaling pathway and PTPRD were indicators of shorter PFS." (PMID 39962074, 2025). "Notably, PROTACs degrading CDK4/6 have shown greater efficacy than traditional CDK4/6 kinase inhibitors in RB1-deficient cancer models, yet the mechanism behind this increased effectiveness remains to be clarified." (PMID 40940326, 2025). "On the other hand, epigenetic silencing of RB1 also frequently occurs in cancer, thus neighbor effects of expression correlation between RB1 and NUDT15 are induced by topologically associated domains, thereby expanding the application of 6MP in patients with cosilencing of RB1/NUDT15." (PMID 40904703, 2025). "It is widely accepted that the factor that triggers this type of cancer is the homozygous loss of the Rb1 gene, according to Knudson’s two-hits hypothesis." (PMID 39845333, 2025). "RB may develop rapidly as a result of epigenetic dysregulation of key cancer pathways, directly or indirectly, caused by the loss of RB1." (PMID 40502639, 2025). "Addressing RB1-deficient cancers poses substantial challenges." (PMID 38672640, 2024). "Investigating how RB1 loss interacts with other genetic alterations or signaling pathways implicated in cancer development and progression could provide valuable insights into the molecular mechanisms driving RB1-deficient cancers." (PMID 38672640, 2024).
cancer (continued). "For example, the identification of BRCA1 and BRCA2 mutations in breast cancer, mutL homolog 1, mutS homolog 6, and mutS homolog 6 mutations in colon cancer, and the RB1 mutation in retinoblastoma is useful for understanding cancer progression in relation to different prognoses and treatments." (PMID 39767566, 2024). "Additionally, targeting RB1 loss-associated cancers with ferroptosis inducers represents a novel therapeutic approach." (PMID 38672640, 2024). "Furthermore, targeting downstream effectors regulated by RB1 presents promising therapeutic approaches for RB1-mutated cancers, overcoming the challenges associated with direct RB1 protein targeting." (PMID 38672640, 2024). "In addition, numerous potential molecular targets have been identified, but the comprehensive functional validation and prioritization of suitable targets for selective therapy represent the initial steps in developing novel treatments for RB1-mutated cancers." (PMID 38672640, 2024). "While many cellular functions and binding proteins have been generally revealed, the precise pathological roles of RB1 loss and its downstream effectors in distinct steps of tumorigenesis and various types of cancers largely remain unknown." (PMID 38672640, 2024). "RB1 is frequently mutated in a number of cancers (7% in total, according to TCGA database), including sarcoma, bladder, endometrial, ovarian, breast, prostate and non-small cell lung (NSCLC) cancers, and the Rb protein is inactivated by high CDK4/6 or CDK2 activity." (PMID 38279263, 2024). "Therefore, it holds promise to target RB1/E2F downstream effectors in the treatment of RB1 mutation cancers." (PMID 38672640, 2024). "However, RB1 loss can also confer advantages, manifesting in diverse mechanisms and vulnerabilities during cancer development." (PMID 38672640, 2024). "Consequently, the detection of RB1 and its associated products is critical for prognostic assessment in cancer." (PMID 39664374, 2024). "However, mutations in RB1 or aberrant pRB phosphorylation can disrupt cell cycle control, promoting cancer development or progression." (PMID 39664374, 2024). "Effective therapeutic strategies against RB1-deficient cancers remain elusive." (PMID 36928314, 2023). "In this issue of the JCI, Wang and colleagues examined how RB1 loss may sensitize cancer cells to ferroptosis inducers through elevation of ACSL4, a key enzyme that promotes lipid peroxidation and triggers ferroptosis." (PMID 37183818, 2023). "RB1 is a tumor suppressor gene that is mutated in various human cancers." (PMID 37441425, 2023). "This suggests that B7H3-PBD-ADC may be considered for treatment of RB1-deficient cancers following platinum resistance." (PMID 37725435, 2023). "Some evidence demonstrated that RB1 mutation increases DNA damage and instability in cancer cells." (PMID 37937640, 2023). "Moreover, RB1 mutation had SL interaction with PARP3 knockdown in the RNA interference screening data set (Cancer Dependency Map [DepMap] Portal, Achilles)." (PMID 37937640, 2023). "Overexpression of p16/CDKN2A in cancer cells has been generally related to RB1 loss of function." (PMID 37964967, 2023). "However, these treatments are ineffective for the large proportion of cancers that have CDK4/6 or Rb1 mutations." (PMID 37484531, 2023).